CUX2 (cut like homeobox 2)
Diseases named in the same sentence as CUX2 in open-access papers:
CUX2 is named in the same sentence as 59 diseases in open-access papers, as found by Europe PMC text mining. Sharing a sentence is not in itself a finding about the gene and the disease. The quoted sentences say what the papers report.
gout (9 papers, 2016 to 2023). A condition characterized by painful swelling of the joints, which is caused by deposition of urate crystals. "An intergenic SNP rs2188380 located between MYL2 and CUX2 gene, and rs4766566 of CUX2 gene were associated with gout in two reports of Japanese male population." (PMID 30123371, 2018). "Recently, a genome-wide association study identified an association between gout and a single nucleotide polymorphism (SNP) rs2188380, located on an intergenic region between MYL2 and CUX2 on chromosome 12." (PMID 27181629, 2016).
epilepsy (5 papers, 2020 to 2024). A brain disorder characterized by episodes of abnormally increased neuronal discharge resulting in transient episodes of sensory or motor neurological dysfunction, or psychic dysfunction. "Recent reports found other CUX2 missense variants as genetic contributors to kainic acid-induced epilepsy." (PMID 37644171, 2023). "Hippocampal sclerosis is the major entity for structural/metabolic epilepsy, and therefore the CUX2 variants in patients with TLE would contribute to the association with epilepsy at 12q24 in Japanese population." (PMID 35581205, 2022). "Together, these observations suggest that the CUX2 variants present in patients with epilepsy cause loss-of-function of the protein." (PMID 35581205, 2022). "To investigate the functional impacts of CUX2 variants appeared in patients with epilepsy, we transfected HeLa.S3 cells with expression constructs of wild-type (WT) and the five variants (p.R34W, p.D337N, p.P454L, p.W958R, and p.E1283K)." (PMID 35581205, 2022). "Because of the loss-of-function nature of epilepsy-associated CUX2 variants, we next investigated Cux2-KO mice." (PMID 35581205, 2022). "Additionally, a region in the human genome that includes CUX2 is shown to be implicated in the pathology of epilepsy." (PMID 39702044, 2024). "CUX2 is therefore one of the most promising candidate genes in this 12q24 epilepsy-associated region, but the mutation reported in rare EEs may not be enough to explain the association detected in the Japanese GWAS study." (PMID 35581205, 2022). "CUX2 gene encodes a transcription factor that controls neuronal proliferation, dendrite branching and synapse formation, locating at the epilepsy-associated chromosomal region 12q24 that we previously identified by a genome-wide association study (GWAS) in Japanese population." (PMID 35581205, 2022). "Nevertheless, our finding that CUX2 is expressed in transient but critical SP neurons of neocortical development further stresses the importance of CUX2 mutations associated with neurodevelopmental disorders, such as autism and epilepsy." (PMID 33671178, 2021). "CASP also showed variants in epilepsy patients including TLE at the unique C-terminus and we further found that the CASP physically binds to CUX2." (PMID 35581205, 2022). "We carried out a targeted sequencing of CUX2 in 271 Japanese patients with variable epilepsies consisting of 116 genetic generalized epilepsies and 155 structural/metabolic ones." (PMID 35581205, 2022). "Thus, L2–3_Cux2 and L5–6_Fezf2 subtypes co-clustered with Sst_Tac1 and Vip_Cbln1 subtypes, whereas L3_Cux2_Prss12 co-clustered with Pvalb_Sulf1, which might underlie local neuronal networks with most strongly affected in the epilepsy transcriptome." (PMID 33028830, 2020). "In this study, we performed targeted sequencing analyses of CUX2, CUX1 and CASP on 271 Japanese patients with a variety of epilepsies, and found that CUX2 missense variants predominantly appear in TLE patients, in that eight of 68 TLE patients (12%) had CUX2 variants." (PMID 35581205, 2022). "Therefore, the CUX2 recurrent variant in EEs may not be enough to explain the genome-wide association with epilepsy at the 12q24 region in Japanese population." (PMID 35581205, 2022).
atrial fibrillation (4 papers, 2018 to 2022). A disorder characterized by an electrocardiographic finding of a supraventricular arrhythmia characterized by the replacement of consistent P waves by rapid oscillations or fibrillatory waves that vary in size, shape and timing and are accompanied by an irregular ventricular response. "Even though previous studies have associated variation in CUX2 with Type 1 diabetes, coronary artery disease, atrial fibrillation and most recently with AAM, our novel signals appear to be distinct and infrequent in populations of European descent." (PMID 30044860, 2018). "CUX2 has been reported to be associated with atrial fibrillation in Japanese populations and also as a risk factor for ischemic stroke, while PSMB8 is a component of immunoproteasome LMP7, which is elevated in ischemic stroke and contributes to neuroinflammation." (PMID 35328807, 2022).
diabetes (4 papers, 2018 to 2023). "These open chromatin regions were significantly enriched in binding sites of CUX2 and HNF6 as well as several other TFs with previously established functions in pancreatic development and links to monogenic diabetes, including HNF1B, FOXA2, and PDX1." (PMID 31883919, 2020).
autism (3 papers, 2021 to 2024). Persistent deficits in social interaction and communication and interaction as well as a markedly restricted repertoire of activity and interest as well as repetitive patterns of behavior. "Cells in the later pseudotime stage exhibited specific enrichment in synaptic pathways, characterized by the upregulation of several neuronal markers, including CUX2, glutamate metabotropic receptor genes (GRM1, GRM2, and GRM3), and several autism risk genes, including PTEN, SCN2A, and SHANK2." (PMID 39363111, 2024).
epileptic encephalopathies (3 papers, 2022 to 2023). "A recurrent de novo missense variant within the first CUT repeat of CUX2 causes CUX2-related epileptic encephalopathy." (PMID 37644171, 2023). "In summary, patients with de novo CUX2 variants have developmental and epileptic encephalopathies characterized by developmental delay, speech delay, movement disorders, and autistic behavior." (PMID 35846140, 2022).
multiple sclerosis (3 papers, 2024 to 2026). A progressive autoimmune disorder affecting the central nervous system resulting in demyelination. "CUX2-expressing neurons are particularly vulnerable to damage induced by multiple sclerosis, showing upregulation of stress pathway genes." (PMID 39702044, 2024). "Previous studies have shown that upper cortical layer thinning occurs in progressive human multiple sclerosis (MS) and that cortical layer 2 and layer 3 (L2/3) excitatory neurons (L2/3ENs) that express CUT-like homeobox 2 (CUX2) are selectively vulnerable to degeneration." (PMID 41922773, 2026).
Type 1 diabetes (3 papers, 2018 to 2024). "Among the four SNPs shared by HbA1c and PCOS (rs8047587, rs1265564, rs2238689 and rs4731113), the most significant (rs1265564, pCPASSOC=2.91×10–13) was near CUX2, a gene that is expressed in neural tissues and that has previously been reported to be associated with insulin-dependent diabetes." (PMID 35771237, 2022). "Genome-based approaches for identifying genetic polymorphisms associated with Type 1 diabetes (such as IL-2RA and CUX2) have revealed specific SNPs (such as PTPN22, IL-10, IL-27, and IL18RAP) with contrasting effects on the development of Type 1 diabetes." (PMID 38474087, 2024).
bipolar disorder (2 papers, 2021 to 2022). A disorder of the brain that causes unusual shifts in mood, energy, activity levels and the ability to carry out day-to-day tasks. "CUX2, on the other hand, is a hotspot for de novo missense mutations in NDDs, including ASD and has also been associated with bipolar disorder." (PMID 34133916, 2021).
breast carcinoma (2 papers, 2019 to 2022). "The aberrant overexpression of CUX2 in breast cancer cells suggests that elevated ROS levels in cancer cells can select rare cells that express any protein able to accelerate the repair of oxidative DNA damage." (PMID 36176767, 2022). "Yet, a genome-wide shRNA screen revealed that CUX2 is required for proliferation in several breast cancer cell lines." (PMID 36176767, 2022).
coronary artery disease (2 papers, 2018 to 2021). "Additionally, the CUX2 gene has been investigated in genome association studies related to serum uric acid levels, coronary artery disease, and hypertension." (PMID 34054925, 2021).
generalized epilepsies (2 papers, 2021 to 2022). "In addition, Cux2 was shown to regulate dendrite development, spine development, and synapse formation of projection neurons placed in mouse upper neocortical layers, while CUX2 mutations in humans were associated with generalized epilepsy." (PMID 33671178, 2021). "None of patients with genetic generalized epilepsies showed CUX2 variants except for silent variants." (PMID 35581205, 2022).
ischemic stroke (2 papers, 2016 to 2022). A stroke disorder caused by obstruction of blood flow to the brain, due to thrombotic (local blood clot formation) or embolic (due to a blood clot or other material traveling from another site) event. "Interesting, CUX2 loci were also significantly associated with ischemic stroke." (PMID 27203392, 2016).
metabolic syndrome (2 papers, 2018). A cluster of metabolic risk factors for CARDIOVASCULAR DISEASES and TYPE 2 DIABETES MELLITUS. "The intergenic variant rs12229654 between MYL2 and CUX2 showed a pleiotropic effect associated with metabolic syndrome, HDL, and glycemic traits." (PMID 30382898, 2018). "All but four of the mapped genes (SIK3, SIDT2, UBASH3B, and CUX2) had been previously reported to be associated with metabolic syndrome, as indicated by a keyword search of “metabolic syndrome” in the GWAS catalog." (PMID 30382898, 2018). "The relation of the individual SNPs, including those on SIK3, SIDT2, UBASH3B, and CUX2, to metabolic syndrome was further examined by single-SNP–multi-trait analysis, adjusted for age and sex." (PMID 30382898, 2018). "SNPs on the UBASH3B and CUX2 genes could not be identified by single-SNP–multi-trait analysis, whereas the association of UBASH3B and CUX2 with metabolic syndrome-component traits was reported in the GWAS catalog." (PMID 30382898, 2018).
Seizure (2 papers, 2022 to 2024). A seizure is an intermittent abnormality of nervous system physiology characterized by a transient occurrence of signs and/or symptoms due to abnormal excessive or synchronous neuronal activity in the brain. "Seizure severity was also significantly higher in Cux2-KO female mice." (PMID 35581205, 2022).
Abdominal obesity (1 paper, 2021). Excessive fat around the stomach and abdomen. "As shown in our results, rs76892715 in the CUX2 region was associated with the WHR, a trait representing abdominal obesity in men." (PMID 34054925, 2021).
Anxiety (1 paper, 2017). Intense feelings of nervousness, tension, or panic often arise in response to interpersonal stresses. "Many of the anxiety-related genes that contributed to these ontological terms have been previously implicated in psychiatric-related disorders, such as CUX2, SYN3, and JAG246,47." (PMID 29225348, 2017).
Burkitt lymphoma (1 paper, 2024). A rare form of malignant mature B-cell non-Hodgkin lymphoma. "The data indicated the significant expression of CUX2 in selected B-cell lines derived from Burkitt lymphoma (RAMOS), diffuse large B-cell lymphoma (SU-DHL-4, WSU-DLCL2) and Hodgkin lymphoma (DEV)." (PMID 38474011, 2024).
colorectal adenoma (1 paper, 2018). An adenoma that arises from the colon or rectum. "Using genome-wide DNA methylation analysis, we identified novel aberrant methylation profiles of genes including HLX, CUX2, MKX, NRG3 and PDGFRA associated with the colorectal adenoma-carcinoma sequence progression." (PMID 29945573, 2018).
Developmental and epileptic encephalopathies (1 paper, 2022). "Developmental and epileptic encephalopathies (DEE) caused by heterozygous deleterious variants in Cut Like Homeobox2 (CUX2) is rare." (PMID 35846140, 2022).
embryonal carcinoma (1 paper, 2022). A non-seminomatous malignant germ cell tumor characterized by the presence of large germ cells with abundant cytoplasm resembling epithelial cells, geographic necrosis, high mitotic activity, and pseudoglandular and pseudopapillary structures formation. "Among expression-related genes, CDX4 and FOXD3 were significantly overexpressed in embryonal carcinoma, whereas CUX2 and RPS6KA5 were increased in seminoma." (PMID 36713456, 2022).
leukemia (1 paper, 2024). A malignant (clonal) hematologic disorder, involving hematopoietic stem cells and characterized by the presence of primitive or atypical myeloid or lymphoid cells in the bone marrow and the blood. "To find CUX2 and ONECUT2 positive models for further analyses and experiments, we screened 100 leukemia/lymphoma cell lines using our benchmark RNA-seq dataset LL-100." (PMID 38474011, 2024).
liver steatosis (1 paper, 2021). "This complex interaction between sex hormones, GH signaling and liver steatosis may converge on Cux2 contributing to the perturbation of sex-biased gene expression, such as that of Fmo3 and Acot3, in all four mice models of NAFLD tested herein." (PMID 34576136, 2021).
metabolic epilepsy (1 paper, 2022). Metabolic epilepsies are conceptualized as having a distinct metabolic abnormality that has been demonstrated to be associated with a substantially increased risk of developing epilepsy in appropriately designed studies. "All of patients carrying CUX2 missense variants belonged to the subgroup of structural/metabolic epilepsy." (PMID 35581205, 2022).
neuroblastoma (1 paper, 2020). Neuroblastoma (NB) is the most common solid, extracranial childhood tumor. "There was a partial rescue of cell death in SKNMMMYCN cells in the presence of doxycycline when CUX2 was ectopically expressed, suggesting that CUX2 is important for oxidative stress in MYCN-amplified neuroblastomas." (PMID 32060267, 2020). "The CUX2 promoter is epigenetically repressed by H3K27me3 in ATRX-mutant neuroblastomas and not induced in SKNMM cells in the presence of doxycycline." (PMID 32060267, 2020). "CUX2 is a direct MYCN target and is upregulated in MYCN-amplified neuroblastomas but not ATRX-mutant neuroblastomas." (PMID 32060267, 2020).
osteoarthritis (1 paper, 2022). A noninflammatory degenerative joint disease occurring chiefly in older persons, characterized by degeneration of the articular cartilage, hypertrophy of bone at the margins and changes in the synovial membrane. "Among them, SPAG5, CUX2, and THEMIS2 were identified as tissue-specific expressed hub genes, these 3 tissue-specific expressed hub genes have superior diagnostic value in the RA samples compared with osteoarthritis (OA) samples." (PMID 35368701, 2022).
psoriasis (1 paper, 2015). An autoimmune condition characterized by red, well-delineated plaques with silvery scales that are usually on the extensor surfaces and scalp. "Several TFs/uDBPs additionally showed altered expression in blood from psoriasis patients (increased: JUNB, STAT3, DTL, CAT; decreased: CUX2, ZNF559, AVEN, RUVBL1, RAN)." (PMID 25883770, 2015).
seminoma (1 paper, 2022). A radiosensitive malignant germ cell tumor found in the testis (especially undescended), and extragonadal sites (anterior mediastinum and pineal gland). "We found that CUX2 and RPS6KA5 were significantly overexpressed in the TGCT cohort of seminoma, and the same results were obtained by quantitative PCR." (PMID 36713456, 2022).
Stroke (1 paper, 2022). Sudden impairment of blood flow to a part of the brain due to occlusion or rupture of an artery to the brain. "Interestingly, we found that the top 3 molecular targets of miR-451a (OSR1, CUX2, PSMB8) have been previously associated with stroke or studied in relation with brain damage." (PMID 35328807, 2022).
thyroid cancer (1 paper, 2022). "Studies have shown that CUX2 is highly expressed in thyroid cancer and promotes tumor cell invasion and migration." (PMID 36713456, 2022).
cancer (6 papers, 2018 to 2025). A tumor composed of atypical neoplastic, often pleomorphic cells that invade other tissues. "Our findings highlight several known joint susceptibility loci for CAD and cancer, including FKBP5, CUX2, and LMOD1, validating the pleiotropy analysis approach employed by PLACO." (PMID 40874306, 2025). "In addition, the protein encoded by Cut Like Homeobox 2 (CUX2) is a cofactor for DNA damage and repair, and the role of CUT domain proteins in DNA repair is exploited by cancer cells to promote their survival." (PMID 36713456, 2022). "Strikingly, both CUX2 and SATB1 are overexpressed in certain cancer cells where their knockdown increases genomic DNA damage and impairs the capacity of cancer cells to proliferate." (PMID 36176767, 2022). "These cancer cells can adapt by increasing their capacity to repair oxidative DNA damage in part through elevated expression of CUT domain proteins such as CUX1, CUX2, or SATB1." (PMID 34204734, 2021). "While the DNA repair function of CUT domain proteins (CUX1, CUX2, and SATB1) is required for the survival of cancer cells that exhibit high ROS levels, this biochemical activity does not appear to be essential to non-transformed cells in normal physiological situations." (PMID 34204734, 2021).
tumor (5 papers, 2018 to 2024). "CUT-like homeobox 2 (CUX2) is expressed highly in tumor relative to normal samples, and its knockdown decreases the growth and invasive ability of BC cells, whereas the opposite effect is observed for SOX17." (PMID 38769556, 2024). "Notably, among the four genes signature, only the CXCL10 gene was involved in tumor immunity; however, few studies have been conducted in oncology for the other three genes (TRPC7, CUX2, and COL2A1)." (PMID 34276760, 2021). "We anticipate that a panel of markers, such as BPTF, TMCO3, CUX2, combined with classic markers: PHOX2B, TH, DCX, will prove valuable in a variety of clinical settings, including the assessment of tumor, drug resistance, residual disease monitoring and prediction of recurrence." (PMID 29467591, 2018).
neurological diseases (2 papers, 2014 to 2021). "CUX2 is usually expressed in the nervous system, whose disturbance is associated with the occurrence of many neurological diseases." (PMID 34447459, 2021). "Among them, Nptx2, Nedd9, Rorb, Cux2, and Htr3a are involved in neuronal development or associated with neurological diseases." (PMID 25071448, 2014).
CUX2 also shares sentences with these, for which no sentence is quoted: schizophrenia (3 papers); autism spectrum disorder (2); developmental delay (2); Hypertension (2); hyperuricemia (2); intellectual disabilities (2); language delay (2); neurodevelopmental disorder (2); cardiovascular diseases (1); cognitive decline (1); Cognitive impairment (1); cortical dysplasia (1); developmental and epileptic encephalopathy 67 (1); diffuse large B-cell lymphoma (1); glioblastoma (1); Hodgkins lymphoma (1); Insulin resistance (1); lymphoma (1); mental disorder (1); metastatic tumor (1); Motor delay (1); movement disorder (1); neuroendocrine carcinoma (1); pancreatic cancer (1); sexual (1); temporal lobe epilepsy (1).